TRIM21 (tripartite motif containing 21)
Diseases named in the same sentence as TRIM21 in open-access papers (continued):
Sharing a sentence is not in itself a finding about the gene and the disease.
tumor (continued). "Internalized TNFAIP8 recruits the E3 ligase TRIM21 to facilitate STAT1 ubiquitination and degradation, leading to the induction of myofibroblastic CAF-associated features, accompanied by enhanced extracellular matrix deposition and tumor growth." (PMID 41709860, 2026). "Finally, in vivo xenograft experiments were conducted to evaluate the impact of ID1 and TRIM21 on tumor growth." (PMID 40919143, 2025). "Depending on the type of cancer, TRIM21 can act as either an oncogene or a tumor suppressor." (PMID 40768895, 2025). "Paradoxically, co-expression of TRIM21 interrupted the Flag-hSPAR-mediated inhibitory effects on mTOR signaling and cancer proliferation, suggesting the indispensable role of TRIM21 in hSPAR’s anti-tumor functions." (PMID 39875724, 2025). "Recognizing TRIM21 as a tumor suppressor, we sought to identify potential drugs that could enhance its transcription using a library of 2408 FDA‐approved and marketed compounds." (PMID 40652518, 2025). "Notably, progressive depletion of TRIM21 protein expression correlated with advanced pathological staging, suggesting a tumor stage‐dependent suppression pattern." (PMID 40652518, 2025). "Additionally, in HCC, the E3 ubiquitin ligase TRIM21 targets β-catenin for polyubiquitination, reducing its levels and suppressing Wnt signaling, thereby inhibiting tumor cell proliferation and migration." (PMID 40299340, 2025). "TRIM21-mediated ubiquitination is critical for protein stability, activity, modification, or cellular localization of substrate protein, therefore participating in the regulation of tumor metastasis." (PMID 40735642, 2025). "To confirm whether Sorafenib's anti‐tumor activity in ESCC depends specifically on TRIM21, we performed rescue experiments using both in vitro CCK‐8 proliferation assays and in vivo subcutaneous xenograft models." (PMID 40652518, 2025). "To determine whether the tumor suppressive effects of TRIM21 are dependent on ID1, we performed ID1 knockdown in both control and TRIM21‐deleted KYSE30 cells." (PMID 40652518, 2025). "It has been show that in KRAS-mutant PDAC, spleen tyrosine kinase (Syk) and tripartite motif containing 21 (TRIM21) accelerate tumor progression toward malignancy by regulating the ubiquitination of BCAT2 to maintain the catabolism and mitochondrial respiration of BCAAs90." (PMID 41281760, 2025). "By reducing the tumor-derived eAdo levels, TRIM21 boosts CD8 activation." (PMID 41583489, 2025). "And we indicated the tumor volume in the TRIM21‐OE group was larger than that in the control group." (PMID 39739616, 2025). "Based on these findings, we hypothesize that TRIM21 may act as a tumor suppressor in CRC by negatively regulating PRMT1." (PMID 39890802, 2025). "Moreover, TRIM21 has been found to play a multi-faceted role in cellular autophagy, metabolic reprogramming, immune escape, tumor proliferation, metastasis and resistance to cell death by regulating the stability and function of key proteins." (PMID 40735642, 2025). "Here, we hypothesized that TRIM21 may suppress tumor proliferation by influencing the cell cycle process." (PMID 39890802, 2025). "In summary, TRIM21 could influence tumor development and chemosensitivity to replication inhibitors by regulating DNA replication through the TCF3/MCM2/5 axis, suggesting a promising potential for CRC in the clinic." (PMID 40998798, 2025). "Altogether, these findings suggest a potential tumor-suppressive role of TRIM21." (PMID 38720056, 2025). "Moreover, TRIM21 mediated the K63-linked ubiquitination on TAT at K136 to impair its dimerization and mitochondrial location, subsequently inhibiting tumor invasion and migration of gallbladder cells." (PMID 40735642, 2025). "However, when simultaneously suppressing TRIM21 and miR-99a-3p, a marked reduction in tumor size of MGC-803-shTRIM21 xenografts was observed compared to the MGC-803- shTRIM21 group (P < 0.05)." (PMID 38720056, 2025).
tumor (continued). "The results indicated a significant positive correlation between low TRIM21 expression and large tumor size (P < 0.001), poor tumor differentiation (P < 0.001), lymph node metastasis (P < 0.001), distant metastasis (P < 0.001), and advanced TNM stage (P < 0.001)." (PMID 39890802, 2025). "Notably, the impact of TRIM21 on tumor immunity also exhibits a dual nature, as it can either promote or inhibit antitumor immune responses by directly binding to and destabilizing its substrates, including PD-L1." (PMID 39152265, 2024). "TRIM21‐mediated proteolytic regulation of CD73 orchestrates tumour immunogenicity." (PMID 39556022, 2024). "Suppression of TRIM21 antagonized tumor suppression induced by USP7 downregulation." (PMID 38702792, 2024). "Furthermore, TRIM21 was related to the tumor microenvironment (TME), which can directly impact B-cell growth and development and enhance membrane antibody trafficking." (PMID 39768197, 2024). "This suggests the potential role of TRIM21 in modulating tumor immunity." (PMID 39152265, 2024). "More specifically, the role of TRIM21 in tumor autophagy is remains controversial." (PMID 38783335, 2024). "TRIM21 exhibits dual roles in tumors, acting as both a tumor promoter and suppressor." (PMID 39543140, 2024). "These experimental results reveal the important tumor suppressor function of TRIM21." (PMID 39543140, 2024). "TRIM21 was one of the E3 ubiquitin ligase which involved in tumor development." (PMID 39543140, 2024). "Our findings suggest that TRIM21 may be a tumor suppressor and new therapeutic target for intervention of CRC." (PMID 38385081, 2024). "Our findings suggest that tumour-intrinsic TRIM21 may function as a negative regulator of radiotherapy-inducible type-I IFN activation-mediated antitumour immunity." (PMID 36797289, 2023). "Notably, in both tumours and cells, high TRIM21 expression was correlated with a poorer response to ionising radiation (IR)." (PMID 36797289, 2023). "The results of the subgroup analysis showed that the relationship between TRIM21 expression levels and prognosis of patients was influenced by a variety of factors, including tumor types, the ethnicity of the study population, the method of detection and the source of the data analysis." (PMID 37335642, 2023). "A renal orthotopic tumor model was established to further evaluate whether TRIM21 can decrease lipid droplet content in vivo." (PMID 36694250, 2023). "Substrates of TRIM21 might be involved in tumor progression, we carried out immunoprecipitation assays and subsequent MS analysis (IP-MS) of captured complexes." (PMID 37771771, 2023). "Moreover, knockout of TRIM21 sensitized tumor cells to RSL3, and this sensitization was reversed by overexpression of wild‐type TRIM21, but not the E3 ligase‐deficient or binding domain‐deficient mutant of TRIM21." (PMID 37587773, 2023). "In addition, the proportion of CD69+ CD8+ T cells was greatly increased in tumours with TRIM21 depletion." (PMID 36797289, 2023). "We observed the cytoplasmic staining of TRIM21 in tumor cells." (PMID 36982215, 2023). "In addition, the mRNA expression of IFNB1, CCL5 and CXCL10 was markedly increased in TRIM21-KO tumours after IR treatment." (PMID 36797289, 2023). "Next, control or TRIM21 siRNA was mixed with atelocollagen and injected in tumor every day." (PMID 37771771, 2023). "The role of TRIM21 in tumor lipid metabolism has also increased in recent years." (PMID 36694250, 2023).
tumor (continued). "Furthermore, direct injection of TRIM21 small interfering RNA (siRNA) into U87 cell-derived tumors (in vivo treatment with siRNA) is proved to inhibit tumor growth in nude mice." (PMID 37771771, 2023). "TRIM21 is essential for tumor growth and invasion of GBM cells and its upregulation may correlate with β-catenin activation." (PMID 37771771, 2023). "In addition, the weight of residual TRIM21-KO tumours was markedly lower than that of TRIM21-WT tumours." (PMID 36797289, 2023). "Interestingly, both tumor-suppressive and oncogenic roles of TRIM21 have been reported, and mechanisms of these seemingly contradictory roles of TRIM21 in cancer remain elusive." (PMID 36749630, 2023). "Finally, HCT116 cells stably overexpressing TRIM21 xenografted onto nude mice developed significantly larger tumor volumes than control HCT116 cells." (PMID 35048968, 2022). "Recent studies showed that TRIM21 played a controversial role in tumor development." (PMID 35864951, 2022). "This is because TRIM21 overexpression or GABAAR knockout itself could have long lasting effects in regulating tumor metastasis even after the clearance of propofol from blood, thus generating potential confounding influence." (PMID 34263559, 2021). "However, the in vitro data demonstrated the role of GABAAR or TRIM21, by using genetic modifications, in the propofol‐promoted tumor cell adhesion to VECs." (PMID 34263559, 2021). "TRIM21 regulated Src expression and, consequently, tumor cell adhesion and extension." (PMID 34263559, 2021). "In addition, SERPINB5 mutation completely blocked the radioresistant effect of TRIM21, suggesting that TRIM21 acts through SERPINB5 to manipulate tumor cell radiosensitivity." (PMID 32005234, 2020). "The tumor-suppressing activity of TRIM21 has been reported although there may be variability between different cancer types and treatment conditions." (PMID 32228434, 2020). "Tumor stage dependent differential degradation including lysosomal, autophagy mediated or proteasomal mechanisms, such as described by the interaction of Cx43 and TRIM21 an E3 ubiquitin-protein ligase, can modify connexin levels, which need further clarification in tumor development and progression." (PMID 25383624, 2014). "Some studies have revealed that TRIM21 exerts tumor-suppressive effects in certain cancers (for instance, breast cancer, renal cell carcinoma, and cervical cancer), while in other types of cancer (such as glioma, nasopharyngeal carcinoma, and liver cancer), it was reported to promote tumor growth." (PMID 39890802, 2025). "Importantly, our findings indicate that treatment with Sorafenib effectively suppresses ESCC tumor growth by upregulating TRIM21 transcription, suggesting that Sorafenib may offer a superior therapeutic option for certain patients with ESCC." (PMID 40652518, 2025). "Moreover, new research declared that high glucose can switch PTEN from a tumor suppressor to a tumor promoter by triggering its neddylation, and then this neddylated PTEN move to the nucleus and decrease the association of FASN with TRIM21 via dephosphorylating FASN in BC." (PMID 38167440, 2024). "Furthermore, there was a rise in the quantity of Th2/GATA3 expression in the lung metastasis tissues of mice injected with the 4T1Cct6a group compared to 4T1EV, showing a decline in the tumours of the 4T1Cct6a+Trim21 mice group compared to the 4T1Cct6a+Trim21‐ΔRING mouse group." (PMID 39556022, 2024). "However, whether TRIM21 expression in tumours affects antitumour immunity, especially that induced by radiotherapy, is largely unknown." (PMID 36797289, 2023). "Nevertheless, we cannot make assumptions about the development of TRIM21 expression during tumor progression, i.e., whether carcinogenesis leads to increased TRIM21 expression and thus to increased immune cell infiltration or whether immune cell infiltration leads to increased TRIM21 expression." (PMID 36982215, 2023).
tumor (continued). "Thus, TRIM21 knockout contributed to the sensitization of tumor cells to ferroptosis in vivo." (PMID 37587773, 2023). "In addition, the proportions of CD69+ or effector molecule granzyme B (GZMB)+ cells among tumour-infiltrating CD8+ T cells were higher in irradiated TRIM21-KO tumours, indicating the IR-induced activation of the CD8+ T-cell antitumour immune response in TRIM21-KO tumours." (PMID 36797289, 2023). "A growing body of evidence showed that TRIM21 and its dysregulation could be involved in the initiation and progression of multiple types of human cancer, and TRIM21 could serve as either an oncogene or tumor suppressor, varying according to the carcinogenesis effectors and the types of cancer." (PMID 37864041, 2023). "S100A4, cathepsin B, cyclin B1, Annexin A2, S100A10, TRIM21, 14-3-3 ζ/δ, and Ezrin may hence participate in tumor invasion depending on the grade of human CRCs, and protein upregulation during lymph node metastasis also suggests a positive correlation with metastasis in human CRCs." (PMID 32154176, 2020). "Additionally, we found inconsistent TRIM21 expression among the tumor samples." (PMID 30367038, 2018). "Immunoblotting assay was performed to confirm the protein level of STAMBPL1, TRIM21 and AXL in excised orthotopic tumor." (PMID 39527690, 2025). "Collectively, targeting the STAMBPL1/TRIM21/AXL axis can decrease mesenchymal phenotype and potentiate anti‐tumor efficacy of cancer therapy." (PMID 39527690, 2025). "UBE2M has been found to mediate the neddylation of TRIM21 and promote ubiquitination degradation of Von Hippel-Lindau (VHL) tumor suppressor by increasing TRIM21 and VHL interactions." (PMID 40735642, 2025). "TRIM21 has also been found to impair CD8+ T cell activation and anti-tumor immunity in some contexts of cancers." (PMID 40735642, 2025). "IHC staining of tumor tissues acquired on the day of sacrifice showed decreased MCM2, MCM5, BrdU and MKI67 levels in TRIM21 knockdown groups, contrasting with elevated TCF3 levels." (PMID 40998798, 2025). "TRIM21 knockdown restored ID1 levels and promoted tumor cell function, whereas TRIM21 overexpression suppressed these malignant phenotypes and mitigated hypoxia-induced aggressiveness." (PMID 40919143, 2025). "Together, these findings suggest that hypoxia promotes ID1 stabilization predominantly through TRIM21 downregulation, thereby enhancing ID1-mediated signaling during tumor progression." (PMID 40919143, 2025). "To investigate the potential inhibitory effects of TRIM21 on CRC tumorigenesis and metastasis in vivo, we conducted two models: a nude mouse subcutaneous tumor model and a tail vein lung metastasis model." (PMID 39890802, 2025). "Through IHC analysis of GIST tissues, we found low expression of TRIM21 and high expression of MDH2 in resistant tumor tissues." (PMID 38973363, 2024). "Compared with the MDA‐MB‐231CCT6A+TRIM21 group, the MDA‐MB‐231CCT6A+TRIM21‐ΔRING group presented significantly greater tumour volume and tumour weight." (PMID 39556022, 2024). "Hijack of OTUD4 by TGF-β antagonizes IFN-γ/TRIM21 cascade, stabilizing CD73 and inhibiting tumor immunogenicity." (PMID 38530357, 2024). "As a tumor suppressor, overexpression of TRIM21 suppressed cell migration and proliferation, facilitated apoptosis in AGS and MKN45 cells, and limited tumor growth in nude mouse xenograft models." (PMID 39768197, 2024). "This study enhances our understanding of TRIM21's regulatory mechanism in the SNAI family and the role of the ubiquitin–proteasome system in tumor development." (PMID 38702792, 2024). "Our qChIP results showed that MTA1 transcriptionally regulates tumor suppressors, including MTA3 and TRIM21." (PMID 39154024, 2024).
tumor (continued). "Mechanistically, deubiquitylation of CD73 by OTUD4 counteracted its ubiquitylation by TRIM21, resulting in CD73 stabilization inhibiting tumor immune responses." (PMID 38530357, 2024). "The E285K-mAbs were also produced in the dimeric IgA (dIgA) format, whose anti-tumor activity depended on the polymeric immunoglobulin receptor (PIGR), a membrane Ig receptor, whereas that of IgG1 relied on TRIM21, an intracellular IgG receptor." (PMID 38886748, 2024). "At an early stage, pathological IgG can enter tumor cells through the AP2 complex and degrade overexpressed proteins through the TRIM21-mediated ubiquitin pathway, thus achieving antitumor effects." (PMID 37379129, 2023). "We found ten E3 enzymes, among which TRIM21, UBR5 and UBE3C have been widely reported to be involved in tumor metastasis." (PMID 37422473, 2023). "HCC tumor tissues contain high levels of HMOX1, S100A9, TMC7, TRAF3 and TRIM21, whereas the expression of IL8RAP and RGL4 were higher in the control group." (PMID 37171396, 2023). "Knockout of TRIM21 resulted in high expression of HLA-A, B2M, TAP1 and TAP2 in SUNE1 tumour cells isolated from BALB/c nude mice and of B2m, Tap1, Tap2, Tapbp and Earp1 in MC38 tumour cells isolated from C57BL/6 mice." (PMID 36797289, 2023). "Here, the authors engineer a TRIM21 biological PROTAC to demonstrate the benefit of a targeted protein degradation approach to deplete HuR, resulting in tumour growth inhibition in pre-clinical cancer models by altering the HuR-regulated proteome." (PMID 37925433, 2023). "We implanted TRIM21 wild-type (WT) or knockout MC38 cells into C57BL/6 mice and then monitored tumour growth after IR treatment." (PMID 36797289, 2023). "To elucidate the effect of TRIM21 on T-cell-mediated antitumour immunity, we performed gene set enrichment analysis (GSEA) and demonstrated that TRIM21-high tumours showed weak IFN responses, especially the type-I IFN response." (PMID 36797289, 2023). "Several genes associated with the GO category of “Regulation of viral entry into host cells,” TRIM5, TRIM21, TRIM22, and TRIM38 were over-expressed in GBM compared to ODG and non-tumor samples." (PMID 35896929, 2023). "Estimated by Tumor Immune Estimation Resource (TIMER) database, TRIM21 expression is positively related with immune infiltrates, such as B cells, CD4+ T cells, macrophages, neutrophils, and dendritic cells, which are also enriched in the TME." (PMID 36159815, 2022). "Conversely, TRIM21 is trapped by actin bundling and stress fiber formation on a stiffer ECM typical in a tumor and, as such, cannot degrade PFK." (PMID 36140753, 2022). "Previous studies have elucidated that TRIM21, TRIM26, TRIM35, TRIM50, and TRIM56 acted as tumor suppressors by inhibiting tumor cell proliferation, and TRIM3, TRIM16, TRIM21, TRIM25, and TRIM26 negatively regulated migration and invasion in HCC cells." (PMID 35142083, 2022). "Finally, considering the association between TRIM21 rs4144331 SNP and other common somatic genetic changes in OSCC, the constitutional rs4144331 SNP may be an important determinant of predicting tumor recurrence after treatment, response to targeted therapy, and drug toxicity." (PMID 34220328, 2021). "Mechanistically, propofol enhances tumor cell adhesion and extension through GABAAR to downregulate TRIM21 expression, leading to upregulation of Src, a protein associated with cell adhesion." (PMID 34263559, 2021). "The imported IgGs recognized their targets through the Fab-domains while the Fc-domains interact with TRIM21 and triggered the ubiquitin-mediated degradation of RHOC in tumor cells." (PMID 32580738, 2020). "Together our data suggest that LPLUNC1 exerts a tumour-suppressive role by downregulating the NF-κB pathway via inhibition of PHB1 ubiquitination and degradation mediated by TRIM21." (PMID 30886235, 2019).